CD4 (CD4 molecule)
Diseases named in the same sentence as CD4 in open-access papers (continued):
Sharing a sentence is not in itself a finding about the gene and the disease.
otitis (6 papers, 2004 to 2022). "Ear infection and low CD4 count were the most common factors for middle ear pathologies in children living with HIV." (PMID 36453796, 2022). "It has been postulated that OM susceptibility is due to impaired T cell-mediated immunity, with one study demonstrating reduced IFNγ+ memory CD4+ T cells in PBMC from otitis-prone children following challenge with recombinant NTHi antigens (but not SEB)." (PMID 29621281, 2018). "Otitis-prone children had more circulating IFNγ-producing NK cells (p<0.05) and more IFNγ-producing CD4+ (p<0.01) or CD8+ T-cells (p<0.05) than healthy controls." (PMID 29621281, 2018). "Our observation that otitis-prone children have fewer CD4+ T cells but more circulating NK cells, predominantly the activated CD56lo NK cells, in comparison with healthy controls has not, to our knowledge, been reported before." (PMID 29621281, 2018). "In a Leishmania major model involving ID ear infection of metacyclic promastigotes, neutrophil depletion also results in enhanced priming of pathogen-specific CD4+ T cells." (PMID 23853593, 2013). "In general, children with ages between 6 and 12 years and 11 months who had some type of otitis, had CD4+ counts of 75.5 38 × 10-9cel/L above the counts of other children (p = 0.002)." (PMID 17143430, 2006). "The elevated counts of lymphocytes, CD3+, CD4+ cells and CD4+HLA-DR+ cells seen among the otitis prone girls, probably reflects a secondary effect of an activated immune system involving T-helper cells, rather than any immune deficient state." (PMID 15563731, 2004). "Significant increases in absolute counts of lymphocytes (p = 0.004), CD3+ T-cells (p = 0.0087), CD4+ T-cells (p = 0.012) and CD4+HLA-DR+ (p = 0.05) as well as in the percentage of CD3+ T-cells (p = 0.05) in otitis prone (n = 5) compared to otitis free (n = 6) Turner girls was shown." (PMID 15563731, 2004). "In the absence of antigen stimulation, otitis-prone children had more circulating Natural Killer (NK) cells (p<0.01), particularly NKdim (CD56lo) cells (p<0.01), but fewer CD4+ T cells (p<0.01) than healthy controls." (PMID 29621281, 2018).
Parasite (6 papers, 2013 to 2022). "Together, these data demonstrate the beneficial function of the CD4+GzB+ T cell subset against mortality caused by an intracellular parasite, which is independent of decreasing heart parasitism." (PMID 35670567, 2022). "This study indicated that all of cryptosporidium spps infections among pre-ART groups were found significantly associated with lower <200 cells/mm3 CD4 count when compared to the ART experienced patients without this parasite infection in any of CD4 category." (PMID 23442332, 2013).
pericarditis (6 papers, 2016 to 2025). An inflammatory process affecting the pericardium. "However, HIV-positive individuals, particularly those with advanced immunosuppression (CD4 < 200 cells/μL), have a significantly higher risk of invasive pneumococcal disease, including pericarditis." (PMID 40842968, 2025). "Sterile pericarditis increased the number of neutrophils (CD11b+), cytotoxic T cells (CD3+), and T helper cells (CD4+) in the atria." (PMID 37384420, 2023).
pheochromocytoma (6 papers, 2019 to 2022). "We also demonstrated that after successful MBTA therapy of subcutaneous pheochromocytoma, long-term immunological memory is driven by CD4+ T cells." (PMID 34439097, 2021). "We found the heterogeneity of T cells in different adrenal tumor subtypes, that is, compared with CD4 T cells in adrenocortical adenomas, the pheochromocytoma types were mostly manifested by activated CD8+, especially in the anatomic specimens from the ectopic ACTH&CRH secreting pheochromocytoma." (PMID 34905486, 2021). "Furthermore, we demonstrated that after successful MBTA therapy of subcutaneous pheochromocytoma, the long-term immunological memory is driven by CD4+ T cells." (PMID 34439097, 2021). "Intratumoral and stromal CD4+ and CD8+ lymphocytes infiltration in pheochromocytoma and paraganglioma with different degrees of malignancy." (PMID 36568391, 2022). "Resting CD4+ T cells is higher than activated CD4+ T cells and naive CD4+ T cells in COAD, TGCT, BLCA, pheochromocytoma and paraganglioma (PCPG), GBM, UVM and BRCA." (PMID 36105075, 2022). "Moreover, adoptive CD4+ T cell transfer from successfully MBTA-treated mice (i.e., subcutaneous pheochromocytoma) demonstrates the importance of these cells in long-term immunological memory." (PMID 34439097, 2021).
plague (6 papers, 2013 to 2023). Plague is a severe bacterial infection caused by the gram-negative bacterium Yersinia pestis. "The ability of the FL SS to enhance these distinct CD4+ T cell responses against the neisserial fHbp, the plague F1 antigen, and the Salmonella antigens CdtB, SseB, and SipD was investigated and found to significantly increase some of these responses." (PMID 35690803, 2022). "For example, CD4+IL-17+ TRM cells have been demonstrated to be critical for the clearance of B. pertussis, pneumonic Yersinia pestis infection, Mycobacterium tuberculosis and Klebsiella pneumonia." (PMID 38093320, 2023).
pneumococcal pneumonia (6 papers, 2009 to 2025). A febrile disease caused by STREPTOCOCCUS PNEUMONIAE. "Furthermore, it has been demonstrated that CD4+ T cells contribute to protective immunity to invasive pneumococcal pneumonia, as MHC-II-deficient mice, which have severely reduced numbers of CD4+ T cells, are highly susceptible to infection." (PMID 22563306, 2012). "Furthermore, low CD4+ T-cell levels have been shown to be associated with increased risk of bacteraemia in HIV infected patients with pneumococcal pneumonia." (PMID 19376181, 2009). "Recently, the importance of regionally compartmentalized resident memory CD4+ T cells was described in the naturally acquired protection against pneumococcal pneumonia, with superior local tissue protection compared to systemic or central memory responses." (PMID 29360883, 2018). "In a case-control study of patients with pneumococcal pneumonia, 50 PWH on ART with CD4 T-lymphocyte count of >350 cells/mm3 were matched to 100 control patients by age, sex, and comorbidities." (PMID 39067055, 2025). "Pneumococcal pneumonia elicits IFN-γ from neutrophils and results in IFN-γ–producing CD4+ T cells in the lung, which may contribute to AM remodeling analogously to the IFN-γ from CD8+ T cells during adenoviral pneumonia." (PMID 35133985, 2022).
polyendocrinopathy (6 papers, 2012 to 2023). "Furthermore, patients with severe inflammation and immune dysregulation or polyendocrinopathy have depletion of CD25+CD4+ T cell developing a variety of autoantibodies." (PMID 29706856, 2018).
prostate adenocarcinoma (6 papers, 2012 to 2025). "MIDN expression was significantly correlated with the infiltration of CD8+ T cell, CD4+ T cell, B cell, macrophage, neutrophil, and DC both in prostate adenocarcinoma and liver hepatocellular carcinoma." (PMID 40002690, 2025). "This study shows that adoptively transferred female lymphocytes, particularly CD4 T cells, can control the outgrowth of pre-implanted prostatic adenocarcinoma cells." (PMID 22493742, 2012).
protein-energy malnutrition (6 papers, 2016 to 2025). A nutritional deficit that is caused by inadequate protein or calorie intake. "A similar finding was reported by a study done in India where CD4 percentage was found to correlate significantly with presence of protein energy malnutrition in HIV infected children." (PMID 28030557, 2016). "A separate study on protein-energy malnutrition (PEM) found decreased level of thymic hormone and a reduction in CD4+ and CD8+ T cell proliferation due to an abnormality in the maturation of these cell subsets in the thymus." (PMID 40086236, 2025). "Protein-energy malnutrition (PEM) particularly affects the thymus gland, crucial for T-lymphocyte maturation, leading to negative effects on the immature CD4 + CD8+ cell fraction, cell proliferation, and thymic hormone synthesis." (PMID 40086236, 2025).
Pruritus (6 papers, 2017 to 2025). Pruritus is an itch or a sensation that makes a person want to scratch. "However, since CD4+ T cells from Dock8−/− OTII Tg mice also induced itch in vivo on transfer into CAG-OVA mice, antigen availability may be a determinant of the disease induction." (PMID 28067314, 2017). "Produced by activated CD4+ Th2 cells, IL-31 activates the DRG via receptors on C-fiber nerve terminals in the skin to elicit pruritus." (PMID 40677708, 2025). "This supports previous findings that malignant CD4 + T cells obtained from CTCL patients can produce IL-31, and its levels correlate with pruritus severity in advanced stages of the disease." (PMID 39068637, 2024). "Absolute counts of both CD4+CD3+ cells (p = 0.0119) and CD3+CD25+ cells (p = 0.0329) were lower in patients with pruritus." (PMID 29951695, 2018).
Q fever (6 papers, 2014 to 2025). A bacterial infection caused by Coxiella burnetii. "Recent mechanistic studies have indicated that CD4+ T cells and anti-Cb antibodies both contribute to vaccination site reactions in murine models of delayed-type hypersensitivity responses to Q fever vaccines." (PMID 40573946, 2025). "T-cell antigen targets of murine CD4 T-cells in these studies were all chosen based on antigen recognition by human sera of Q fever exposed individuals." (PMID 30828331, 2019). "Also, the protection conferred by CD8+ T cells results in less lung inflammation and decreased bacterial burden in spleens as compared to the protection elicited by CD4+ T cells, suggesting that efficacious vaccines against Q fever should elicit CD8+ T-cell immunity." (PMID 36788233, 2023). "Therefore, the identification of epitopes in the C. burnetii antigens recognized by CD4+ T cells could help design molecular vaccines against Q fever." (PMID 24498044, 2014). "Thus, CD4+ T cells may be responsible for the Q-VAX-induced adverse reactions, future Q fever vaccines should modulate the CD4+ T cell response to reduce inflammation without sacrificing protection." (PMID 39469719, 2024).
rhinitis (6 papers, 2013 to 2024). An inflammation of the mucous membrane lining the nose, usually associated with nasal discharge. "In a murine model of rhinitis, oral administration of B.breve reduced the symptoms and serum specific-IgE, IL-4, IL-10, andincreased CD4+CD25+ T-regulators." (PMID 38687061, 2024). "Previous studies demonstrated that CD4+ T cell counts increase in nasal mucosa of rhinitis patients after allergen challenge." (PMID 24116013, 2013). "Therefore, the aim of our study was to analyse the expression of CD26 and CD126 in CD4+ and CD4− lymphocytes from healthy subjects and patients with AA/NAA or rhinitis." (PMID 31101830, 2019).
salmonellosis (6 papers, 2012 to 2023). Infections with bacteria of the genus salmonella. "Our study provides a critical analysis of LAV-induced CD4+ T cell immunity using a model of murine salmonellosis, and presents acute inflammation as a beneficial response to the development and maintenance of T cell immunity." (PMID 37733817, 2023). "One was an Indian IVDU with CD4 counts <50 cells/ mm3 and having OIs such as Mycobacterium tuberculosis infection and salmonellosis." (PMID 22347442, 2012). "However the most marked reductions are in CD4+ and γδ cells that is likely to lead to reduced production of Th1 cytokines such as interferon-γ that drive the cellular responses associated strongly with clearance and protection against salmonellosis in the chicken." (PMID 23133568, 2012).
secondary progressive multiple sclerosis (6 papers, 2009 to 2025). A multiple sclerosis with a clinical course characterized by a progressive accumulation of neurological disability, independent of relapses, following an initial relapsing-remitting (RR) phase. "Cytotoxic CD4+ T cells occur in supercentenarians making a signature of healthy aging, but can also correlate with active progressive disease as exemplified by CNS-resident CD4+EOMES+GZMB+NR4A2+ T cells in secondary progressive multiple sclerosis." (PMID 41030456, 2025). "For example, patients with secondary progressive multiple sclerosis show elevated numbers of Eomes expressing CD4+ T cells that mark inflammatory disease activity." (PMID 36756120, 2023). "The opposite is true for secondary progressive multiple sclerosis (SPMS), where CNS-resident EOMES+GZMB+NR4A2+CD4+ T cells correlate with active progressive disease." (PMID 39025930, 2024).
serous ovarian cancer (6 papers, 2013 to 2023). "In the present study, we found for the first time that CD4+CD25+FOXP3+ Tregs are associated with outcome specifically in serous ovarian cancer but only in the context of CD8+ T cells." (PMID 24244610, 2013). "We next assessed the particular association between five genes and then a variety of infiltrating immune cells in serous ovarian cancer, such as CD4+/CD8+ T cells, B cells, and macrophages." (PMID 36980477, 2023). "To simulate the OC microenvironment, we co-cultured CD4+ Tregs and Teffs with ovarian serous adenocarcinoma cell line SKOV3 for 3 days." (PMID 33414414, 2021). "Our study sought to investigate the association of tumor-infiltrating CD4+CD25+FOXP3+ Tregs, and other immune factors, with clinical outcome in serous ovarian cancer patients." (PMID 24244610, 2013). "Fifth, the conclusions of this study may only apply to high-grade serous ovarian cancer and the types of TILs are limited to CD3+, CD4+, and CD8+ T cells." (PMID 33718143, 2021).
staphylococcus aureus infection (6 papers, 2013 to 2025). An infectious process in which the bacteria Staphylococcus aureus is present. "Other immune cells are also metabolically affected during infections, including highly glycolytic myeloid-derived suppressor cells that inhibit CD4+ T cell glycolytic activity by lactate secretion in Staphylococcus aureus infection." (PMID 40857407, 2025). "IL‐27 also strongly stimulated CD4+T cell proliferation and Th1 cytokine production by up‐regulating the antigen‐processing capability of DC in the Staphylococcus aureus infection." (PMID 32761753, 2020).
synucleinopathies (6 papers, 2014 to 2025). "The present study revealed that CD4+ cells accumulated within nigral blood vessels and infiltrated the parenchyma of the substantia nigra in individuals affected by synucleinopathy or tauopathy." (PMID 40842561, 2025). "Our findings in human samples are in agreement with those in α-syn tg mice, suggestive of a potential role for CD4+ cells in the inflammatory processes of synucleinopathies." (PMID 32680537, 2020). "In the case of the synucleinopathies, several studies performed in animal models have found that CD4+ T cells are critically involved in the neurodegenerative and neuroprotective antagonistic processes associated to disease 13–17." (PMID 25866630, 2014). "This study also identified discrete populations of α-syn reactive CD4+ T cells that express CXCR4 and IL17A which were present in the cerebro-spinal fluid of synucleinopathy patients and are correlated to the neurodegenerative phenotype." (PMID 35897751, 2022). "As PD is primarily a synucleinopathy and PSP a tauopathy, we also compared the alterations in CX3CL1, microglia, and CD4+ T cells in both neurodegenerative diseases to determine whether there is a difference between pathologies." (PMID 40842561, 2025).
systemic inflammatory response syndrome (6 papers, 2013 to 2024). SIRS is a serious condition related to systemic inflammation, organ dysfunction, and organ failure. "To sum up, we rejected the hypothesis that the increase in CD4+ T cells may have been associated with septic or aseptic systemic inflammatory response syndrome." (PMID 35637935, 2021). "Changes in CD4+ lymphocyte BTLA expression were compared with morbid event development in critically ill ICU patients (11 septic and 28 systemic inflammatory response syndrome subjects)." (PMID 24289156, 2013).
tauopathy (6 papers, 2019 to 2025). Neurodegenerative disorders involving deposition of abnormal tau protein isoforms (tau proteins) in neurons and glial cells in the brain. "This suggests that signals underlying T lymphocyte recruitment in tauopathies might be different for CD4+ versus CD8+ T cells." (PMID 37703311, 2024). "The alterations of CX3CL1, TMEM119, and CD4 in subjects with tauopathy also displayed a similar pattern of inflammatory changes." (PMID 40842561, 2025). "Similarly to what was observed upon treatment with a CSF1R antagonist, prolonged depletion of T cells (via injections of anti-CD4 and anti-CD8 depleting antibodies) reduced the levels of hyperphosphorylated tau and reduced neuronal loss in the APOE4-expressing tauopathy mouse model." (PMID 37580702, 2023). "In a mouse model of tauopathy expressing APOE4, increased T cell receptor clonality was observed within brain infiltrating activated CD4 and CD8 T cells." (PMID 37580702, 2023). "Our previous results showed that misfolded truncated tau protein induced upregulation of CD11a, CD11b, CD18, CD4, CD45 and CD68 in the transgenic rat model of tauopathy." (PMID 31120951, 2019). "Therefore, we quantified the numbers of CD4+, CD3+ and CD8+ T-cell in the brainstem of a transgenic rodent model for tauopathy." (PMID 31120951, 2019). "Here, we hypothesized that the brain-immune communication pathway that is needed to be activated to combat tauopathy involves monocyte mobilization via the C-C chemokine receptor 2 (CCR2)/CCL2 axis, and additional immune cells, such as CD4+ T cells, including FOXP3+ regulatory CD4+ T cells." (PMID 34172073, 2021).
testis cancer (6 papers, 2017 to 2024). "In addition, our results also match findings suggesting that testis cancer antigens elicit spontaneous CD4+ and CD8+ T-cell responses." (PMID 35269507, 2022). "VISTA is constitutively expressed in naïve CD4+ T cells, and normalizes innate and adaptive immune response independently of PD-L1, thus, it is reasonable to compare their expression in testicular cancer." (PMID 33916925, 2021). "We detected evidence of type I (interferon-γ producing), activated (CD69+) CD4+ and CD8+ antigen-specific T cell immunity against cancer-testis (NY-ESO-1) as well as melanocytic lineage (MART-1, gp100) antigens in the absence of therapeutic vaccination." (PMID 29973204, 2018). "CD8+ and CD4+ T-cells responsive against MAGE-A family antigens were also detected in the peripheral blood of seminoma patients, supporting the systemic surveillance of testicular cancer ⁠." (PMID 33916925, 2021).
thalassemia (6 papers, 2009 to 2026). An inherited blood disorder characterized by a decreased synthesis of one of the polypeptide chains that form hemoglobin. "Raised serum ferritin even in the non-overload range positively affects regulatory T cells which might suppress CD4+ and CD 8+ immune cells, increasing the risk of infections in transfusion-dependent thalassemia major patients." (PMID 36945272, 2023). "Non-transfusion-dependent thalassemia patients exhibited a distinct ascending CD4+ lymphocyte pattern, as the number of chimeric alleles was increased (independent samples median test p = 0.056), however, the same was not true for all patients with TDT." (PMID 35252277, 2022). "As previously stated, a low CD4/CD8 ratio is one of the most frequent abnormalities in patients with thalassemias and hemoglobinopathies; thus, HIV disease is an example of negative interactions and bidirectional combination of the hematological with the infectious disease." (PMID 21415996, 2009).